AKT1 (AKT serine/threonine kinase 1)
Diseases named in the same sentence as AKT1 in open-access papers (continued):
Sharing a sentence is not in itself a finding about the gene and the disease.
COVID-19 (continued). "The reduced expression of AKT1/2 suggests decreased cell survival, which, coupled with reduced BCL2L1 expression, may contribute to increased apoptosis and lymphopenia in COVID-19." (PMID 38389037, 2024). "The results show that Diosmetin can highly bind with novel coronavirus-specific proteins and core gene proteins, suggesting that the effect of Diosmetin on BRCA/COVID-19 may be targeted by EGFR, AKT1, and GSK3B proteins." (PMID 36060002, 2022). "The ‘prevalent’ ‘candidate genes’ (ADAM10, ADAM17, AKT1, CTNNB1, ESR1, FGFR1, PIK3CA) might have the most prominent pathophysiological relevance in COVID-19." (PMID 36229517, 2022). "A decrease in the expression of the following genes was also observed in COVID-19-positive patients: RAPGEF1 (p = 0.0091), MAP2K1 (p = 0.038), CEBPB (p = 3.3 × 10−6), STAT6 (p = 0.041), JUN (p = 1.4 × 10−8), PRKACA (p = 0.021), and AKT1 (p = 1.3 × 10−6)." (PMID 36298734, 2022). "The COVID-19 samples presented statistically increased tissue immunoexpression of ACE-2 (p < 0.0001), AKT-1 (p = 0.022), CD44v6 (p < 0.0001), IL-4 (p < 0.0001), MMP-9 (p = 0.004), α-SMA (p < 0.0001), Sphingosine-1 (p < 0.0001), and TGF-β1 (p = 0.0315) when compared to the CONTROL group." (PMID 35008594, 2021). "In addition, VEGF signaling pathway and HIF-1 signaling pathway are also rich in key targets such as AKT1, PIK3CA and PIK3CD, which may be related to the effect of CEP on COVID-19." (PMID 35935817, 2022). "A network pharmacology study showed that quercetin, luteolin, and baicalein were the main compounds of Huopu Xialing Decoction, which might regulate multiple signaling pathways targeting Akt1, MAPK1, cyclin D1 (CCND1), and caspase-8, thus played a therapeutic role on COVID-19." (PMID 34861881, 2021).
osteoporosis (55 papers, 2012 to 2026). A condition of reduced bone mass, with decreased cortical thickness and a decrease in the number and size of the trabeculae of cancellous bone (but normal chemical composition), resulting in increased fracture incidence. "Previous studies have shown that induced AKT1 expression promotes the proliferation of mesenchymal stem cells and ultimately inhibits their apoptosis, thereby alleviating osteoporosis." (PMID 38260098, 2023). "Taken together, our findings indicate that tanshinone can alleviate osteoporosis, which was potentially mediated through modulation of the AKT1 expression." (PMID 35419360, 2022). "Some studies have verified that the inhibition of AKT1 expression would enhance bone turnover markers' expression and extracellular matrix mineralization, which consequently suppresses osteoporosis." (PMID 35154351, 2022). "Researchers found that AKT1 is closely related to the proliferation and differentiation of osteoblasts and the formation of osteoclasts and can be used as a target in the treatment of osteoporosis." (PMID 34671409, 2021). "The lack of AKT1 in the body will lead to the loss of bone mass, which will lead to osteoporosis." (PMID 34649566, 2021). "After screening the core therapeutic ingredients, a PPI network was constructed to determine core targets; our results showed that AKT1, CASP3, EGFR, ESR1, IGF1, MAPK1, and MAPK14 are important for AB–DA treatment of osteoporosis." (PMID 37849727, 2023). "According to topological analysis results, AKT1, MAPK1, ESR1, and SRC are critical genes for RRP to treat osteoporosis, and they have high binding activity with stigmasterol and sitosterol." (PMID 34649566, 2021). "The results of the current study also showed that CTNNB1 and CAV1 were significantly downregulated in the osteoporosis samples, while SHC1, AKT1 and FLNA were upregulated." (PMID 25815782, 2015). "Secondly, the enrichment test of AKT1 in different osteoporosis subtypes was not studied." (PMID 35419360, 2022).
viral infection (53 papers, 2013 to 2025). "The presence of particular AKT1 mutations in HCV-infected individuals suggests a link between viral infection and genetic vulnerability." (PMID 41291320, 2025). "Since its discovery more than 25 years ago, AKT1 has been extensively studied in many cancers as well as in other virus infections." (PMID 37766164, 2023). "KEGG enrichment analyses showed that these differentially expressed genes (DEGs) are significantly represented by the phosphatidylinositol 3‐kinase‐AKT serine/threonine kinase 1 (PI3K‐AKT) pathway, virus infection and focal adhesion." (PMID 34738311, 2021). "The present study demonstrated that coumarin derivative N6 exerted an effective activity against HTNV in vivo and in vitro, and AKT1 was possibly involved in the molecular mechanism of N6 in treating viral infection." (PMID 34938178, 2021). "The molecular docking was conducted on the most significant gene Akt1, which is involved in lung injury, lung fibrogenesis and virus infection." (PMID 33140889, 2020). "Our results clearly demonstrated that ectopic expression of Akt1 or Akt2 in virus-specific CTLs enhanced their antiviral efficacy with strong cell expansion and cytotoxicity in response to intrahepatic viral Ag stimulation and clear viral infection." (PMID 40139836, 2025). "AKT1 upregulated upon virus infection enhances cell adhesion and decreases cell migration." (PMID 35392111, 2022). "Akt1 is a promising drug target to reduce tissue damage and help eliminate virus infection." (PMID 33140889, 2020). "Several studies indicated that heat shock proteins (HSP) are upregulated by viral infection, but also annexin 1 and 2, AKT serine/threonine kinase (AKT1) and hypoxia-inducible factor (HIF1a)." (PMID 32268515, 2020). "Notably, AKT1, FOXO1, and MMP9 were enriched in the RIG-I-like receptor and Toll-like receptor pathways, which are crucial for innate immune responses against viral infections." (PMID 40574839, 2025). "Key identified intermediate nodes AKT1 and MAPK1 were already connected to coronavirus infection and other viral infections, also suggesting that the observed TF changes are initiated by the RIG-I like receptors, thus corresponding to the antiviral response of the host cell." (PMID 35404937, 2022). "At day 3 of viral infection, we found that blocking Akt3, but not Akt1, Akt2, or Akt1 plus 2, resulted in an inhibition of colony growth and obvious floating, dead cells." (PMID 28483982, 2017). "Analogous to MDA-MB-468 cells, AKT is constitutively active in the LNCaP cell line, and viral infection did not significantly impact AKT activation, although moderate downregulation of total AKT1 was observed." (PMID 27849011, 2016).
ischemic stroke (52 papers, 2012 to 2026). A stroke disorder caused by obstruction of blood flow to the brain, due to thrombotic (local blood clot formation) or embolic (due to a blood clot or other material traveling from another site) event. "Notably, MAPK3, MAPK1, HSP90AA1, STAT3, PIK3R1, PIK3CA, and AKT1 were the main target proteins involved in the pathogenesis of ischemic stroke with Qi deficiency and blood stasis syndrome." (PMID 35401166, 2022). "The level of active Akt1 is strongly correlated with the amount of cell death during ischemic stroke." (PMID 29290948, 2017). "IL-6, AKT1, VEGFA, STAT3, TNFα, etc., were the core target of phenolic acids in preventing ischemic stroke." (PMID 36778026, 2023).
Proteus syndrome (50 papers, 2011 to 2026). Proteus syndrome (PS) is a very rare and complex hamartomatous overgrowth disorder characterized by progressive overgrowth of the skeleton, skin, adipose, and central nervous systems. "The diagnostic criteria for Proteus syndrome include evaluation for a pathogenic variant of the AKT1 gene, which contributes to the mosaicism found in the disease as well as evaluating for certain common phenotypic features." (PMID 41522263, 2026). "A woman in her 30s with a known case of Proteus syndrome with AKT1 mutation came to our institution for a routine follow‐up." (PMID 41522263, 2026). "Proteus syndrome, associated with AKT1 mutations, is less commonly detected prenatally, as its hallmark progressive asymmetric overgrowth usually becomes apparent during childhood." (PMID 40861611, 2025). "Different studies have shown the association of mutations in the AKT1 gene with Proteus syndrome, Cowden syndrome, and cancer." (PMID 37511907, 2023). "Further, the AKT1 gene mutations are also reported to be associated with other diseases such as Proteus syndrome and Cowden syndromes." (PMID 37511907, 2023). "The other disease-causing genes includes AKT1 for Proteus syndrome, MAP3K3 for verrucous venous malformation (VVM), GNA11 for DCMO, RASA1 and EPHB4 with germline or somatic mutations for capillary malformation-arteriovenous malformation (CM-AVM), and so on." (PMID 37658401, 2023). "Proteus syndrome is a rare sporadic and progressive overgrowth disorder caused by a post-zygotic activating variant of AKT1." (PMID 35461279, 2022). "Mosaic gain-of-function mutations in AKT1 cause Proteus syndrome (OMIM: 179620), while somatic gain-of-function mutations in PI3KA cause CLAPO (OMIM: 613089) and CLOVE (OMIM: 612918) syndromes." (PMID 35806420, 2022). "Proteus syndrome is a complex systematic disorder with an AKT1-activating mutation that comprise with asymmetric tissue overgrowth involving almost the entire body and skin manifestations such as cerebriform connective tissue nevi and epidermal nevi." (PMID 34980271, 2022). "The past ISSVA classification mentioned the AKT1 gene as the causal agent of capillary, venous, and lymphatic malformations exclusively associated with Proteus Syndrome." (PMID 35740845, 2022). "AKT1 is another gene in the PI3K/AKT signaling pathway that has been seen with activating mutation associated with Proteus syndrome." (PMID 35225964, 2022). "Proteus syndrome, characterized by progressive asymmetric growth of multiple tissue types, is caused by somatic mosaicism for an activating AKT1 mutation." (PMID 33263939, 2021). "Proteus syndrome has been almost exclusively associated with the mosaic c.49G > A p.(Glu17Lys) pathogenic gain-of-function variant in AKT1, also observed in cancers." (PMID 34944785, 2021). "Proteus syndrome is associated with a somatic activating AKT1 mutation and has distinct clinical findings." (PMID 34238334, 2021). "Proteus syndrome is associated with a mosaic, somatic activating variant in AKT1 (typically c.49G >A p.Glu17Lys) which is an important aid in diagnosis." (PMID 33753828, 2021). "A clinical criteria scoring system and specific molecular test lead to the diagnoses of classic Proteus syndrome or AKT1-related overgrowth spectrum when a variant is found in a patient with few of the typical features." (PMID 34944785, 2021). "Four patients who met the diagnostic criteria of Proteus syndrome carry mosaic AKT1 p.Glu17Lys variant." (PMID 33054853, 2020). "In the 4 patients who met the diagnostic criteria of Proteus syndrome, we identified an AKT1 c.49G > A (p.Glu17Lys) variant, which is the only variant known to cause Proteus syndrome." (PMID 33054853, 2020).
Proteus syndrome (continued). "The AKT inhibitor ARQ-092 led to the remission of a cancer in a patient with Proteus Syndrome carrying an AKT1 mutation, and is currently undergoing clinical evaluation in PROS." (PMID 31752127, 2019). "ARQ-092 is additionally being investigated for the primary treatment of Proteus syndrome, an overgrowth disorder resulting from an activating mutation in AKT1 (AKTG49A)." (PMID 31540244, 2019). "Somatic mutations of (a) AKT1 E17K have been associated with Proteus syndrome and a number of cancers; (b) AKT2 with lipodystrophy and hypoglycaemia; and AKT3 with neuronal migration defects and hemimegalencephaly." (PMID 29549527, 2018). "We report encouraging results demonstrating inhibition of AKT by ARQ 092 in cells and tissues harboring AKT1 E17K mutations from patients with Proteus syndrome." (PMID 26657992, 2015). "A somatic activating mutation in AKT1, c.49G>A, pGlu17Lys, that results in elevated AKT signaling in mutation-positive cells, is responsible for the mosaic overgrowth condition, Proteus syndrome." (PMID 26657992, 2015). "This indicates that the AKT1 E17K mutation exists in a heterozygous, mosaic state in patients with Proteus syndrome and that at the cellular level the phenotype is a combination of the activity of both alleles." (PMID 26657992, 2015). "There is an association between genital tract tumors and Proteus syndrome, a rare, sporadic, and progressive entity, characterized by a postnatal overgrowth in several tissues caused by a mosaic mutation in the AKT1 gene." (PMID 26558123, 2015). "Other sporadic disorders caused by somatic mosaic events rather than germline mutations include activating mutations of AKT1 associated with Proteus syndrome and gain of function mutations in PIK3CA causing macrodactyly." (PMID 24497998, 2014). "Once the human safety profile has been well established, it will be tempting to explore them in patients with Proteus syndrome and/or hypoglycemia caused by AKT1 or AKT2 mutation, respectively." (PMID 24978597, 2014). "More recently, E17K mutation in AKT1 has been associated with Proteus syndrome and a similar mutation in AKT2 was found in patients with rare hypoglycemia." (PMID 24978597, 2014). "It was recently shown that hamartomata that are part of the Proteus syndrome arise from somatic activating mutations in oncogene AKT1." (PMID 23209713, 2012). "For example, a somatic mutation in AKT1 causes Proteus syndrome and germline PTEN mutations can cause macrocephaly and overgrowth." (PMID 22190405, 2011). "Further downstream in the pathway, somatic variants in AKT-1 (encoding protein kinase B or AKT), which regulates cell survival, lead to the development of the soft tissue and dermatological findings pathognomonic of Proteus syndrome, particularly cerebriform connective tissue naevi." (PMID 39254838, 2025). "Moreover, AKT1 mutations are associated with Proteus syndrome, characterized by an increased risk of thromboembolism." (PMID 39035772, 2024). "Furthermore, the AKT1 gene mutations are also associated with Proteus syndrome, Cowden, and Cowden-like syndromes." (PMID 37511907, 2023). "In addition, we identified a novel AKT1 p.Q79K mutation in Proteus syndrome and MAP3K3 p.E387D mutation in verrucous venous malformation." (PMID 37658401, 2023). "Additionally, Proteus syndrome has capillary, venous, and lymphatic malformations, and asymmetrical somatic overgrowth from AKT1 mutation." (PMID 35225964, 2022). "Nine samples contained P/LP variants with VAF < 0.05, ddPCR probes were available to confirm variants in six of these samples and two variants were confirmed with a restriction enzyme digest designed to detect the known causative variant in AKT1 for Proteus syndrome." (PMID 33832433, 2021).